TPM1 (tropomyosin 1)
Diseases named in the same sentence as TPM1 in open-access papers (continued):
Sharing a sentence is not in itself a finding about the gene and the disease.
Type 2 diabetic (1 paper, 2016). "In Type 2 diabetic patients leukocyte mRNAs encoding HMW TPM1 isoforms from exon 1a were markedly decreased (0.55 v 1.00, p = 0.019)." (PMID 27649540, 2016). "Lower levels of TPM1 mRNA reduce tumour suppression and could contribute to increased cancer risk in Type 2 diabetes." (PMID 27649540, 2016). "Expression of HMW isoforms from TPM1 is decreased in Type 2 diabetes." (PMID 27649540, 2016). "The aim was to determine changes in expression of isoforms from TPM1 and TPM4 genes in leukocytes from Type 2 diabetic patients and to use the leukocyte cell line THP1 to identify possible mediators of changes in the patients." (PMID 27649540, 2016). "We have investigated the expression of tropomyosin isoforms from TPM1 and TPM4 in patients with Type 2 diabetes." (PMID 27649540, 2016). "The results of this study strongly indicate that there are decreased levels of expression of HMW isoforms from TPM1 and TPM4 in leukocytes from Type 2 diabetic patients and that these are due to elevated levels of inflammatory cytokines in those patients." (PMID 27649540, 2016).
tumor (117 papers, 2007 to 2026). "The expression of IGFBP3 and TPM1, on the other hand, has been closely associated with tumor cell growth and survival, further emphasizing the potential significance of these genes in the context of DLBCL." (PMID 38240686, 2024). "TPM1 acts as a tumour suppressor and its loss promotes cell proliferation and metastasis by inducing epithelial to mesenchymal transition and regulating cytoskeletal remodelling in CRC51." (PMID 40603632, 2024). "There has been discussion on the physiological function of TPM1 in various malignancies; tumor types have been linked to metastasis and cancer progression at both higher and lower expression levels." (PMID 38735911, 2024). "The TPM1 gene and its products are strongly associated with cancer, which is usually considered as tumor suppressors, and TPM1 overexpression induces apoptosis in cancer cells during cancer progression." (PMID 37686101, 2023). "As a member of the tropomyosin (TM) family, TPM1 encodes high molecular weight TM isoforms which regulate the proliferation, motility, invasion, and metastasis of tumor cells." (PMID 35477379, 2022). "TPM1 gene is a member of a tumor-associated protein family (the tropomyosin family) - it plays an important role in tumor-specific variations of actin filament aggregation via stress fiber modulation and actin cytoskeleton modification." (PMID 32695477, 2020). "The mechanism by which miR-21 promotes tumor invasion and metastasis is associated with its ability to repress multiple tumor suppressor genes, including tropomyosin 1 (TPM1), programmed cell death 4 (PDCD4), and maspin." (PMID 26769851, 2016). "TPM1–4 was associated with some tumor‐infiltrating immune cells in HCC." (PMID 34850589, 2022). "Furthermore, the cytoskeletal protein tropomyosin 1 (TPM1) encoded gene is an accepted tumor suppressor." (PMID 31683635, 2019). "Mechanistically, miR-21 is postulated to promote tumor progression by inhibiting tumor suppressor genes, such as TPM1 and PDCD4, which play a crucial role in controlling invasion and inducing cell death through apoptosis." (PMID 41511367, 2026). "Most functional data stem from studies on other epithelial cancers, where TPM1 and TPM2 have been implicated as tumor suppressors." (PMID 40937226, 2025). "Conversely, oncomiRs such as miR-21 target tumor-suppressor genes, including PTEN and TPM1, promoting tumor cell survival and growth." (PMID 41154621, 2025). "Tropomyosin-1 (TPM1) was shown to be downregulated in solid tumors and was previously identified as a novel tumor suppressor gene." (PMID 41231336, 2025). "In this context, our study contributes to understanding the oncogenic role of miR-183-5p as an onco-miR, showing its ability to suppress TPM1, a tumor suppressor, and thereby promoting urothelial carcinogenesis." (PMID 41231336, 2025). "TPM1 is characterized as a tumor suppressor and can induce apoptosis in cancer cells, suppressing cancer progression." (PMID 39356055, 2024). "Drawing from the TCGA-BLCA cohort, we discovered that RAD54B and KPNA2 expressions rose in tumor tissues, whereas TPM1 expressions declined in comparison to corresponding normal tissues." (PMID 38735911, 2024). "The TPM1 gene is considered a member of the tumor-related protein family, originally known as the tropomyosin family." (PMID 38217031, 2024). "There is solid evidence that TPM1 can act as a tumor-suppressor gene in oral squamous cell carcinoma (OSCC)." (PMID 37686101, 2023). "This formed a regulatory network: lncRNA MEG3 sponge adsorbed miR-96 and directly increased the expression of tumor-suppressor TPM1." (PMID 37686101, 2023). "From 1895 metastasis-related genes, they found that the expression of SLC2A1, CDCA8, ATG10, and HOXD9 was higher in HCC tumor tissue whereas the expression of TPM1 was lower." (PMID 37974228, 2023).
tumor (continued). "It targets and inhibits the expression of TNFAIP1 and TPM1, which are considered to be tumor-suppressive factors and are often used as targets of miRNAs including miR-558 and miR-224, thereby allowing tumor progression." (PMID 37686101, 2023). "TIMER2.0 was used for investigating the relevance of TPM1–4 to tumor‐infiltrating immune cells in HCC." (PMID 34850589, 2022). "Studies have shown that TPM1 is a very important tumor suppressor, and its expression level is low in many solid tumors." (PMID 35734544, 2022). "TPM1 is regarded as a tumor suppressor and overexpression of TPM1 can induce cancer cell apoptosis in the progression of cancer." (PMID 34850589, 2022). "Particular attention was paid to three of them: Histone H2A type 1-B/E (H2A1B), macrophage migration inhibitory factor (MIF) and Tropomyosin alpha-1 chain (TPM1), which are present only in the tumor zones of R-GBM, in particular in CORE." (PMID 35216175, 2022). "Afterward, we studied the relationship between TPM1–4 and tumor‐infiltrating immune cells in HCC using the TIMER2 database." (PMID 34850589, 2022). "The correlation of SPARC and TPM1 expression and clinicopathological parameters, including tumor stage, tumor grade and lymphnode metastases, was analyzed by UALCAN database." (PMID 35477379, 2022). "TPM1 is an actin-binding cytoskeletal protein with a recognized tumor suppressor function in a lot of cancers." (PMID 35216175, 2022). "Known targets of miR-21 include SERPINB5 (also known as maspin) and PTEN, along with tumor suppressors TPM1 (tropomyosin 1) and PDCD4 (programmed cell death 4 protein)." (PMID 36010971, 2022). "The results displayed that the expression of miR-183 was significantly decreased in tumor tissues of mice after treatment of exosomes carrying inhibition of miR-183 (p < 0.05) while the expression of TPM1 was significantly increased." (PMID 33653339, 2021). "All in all, LINC01116 facilitates CRC cell proliferation and tumor angiogenesis by negatively regulating TPM1 expression." (PMID 33499872, 2021). "qRT-PCR and Western blot revealed that sh-LINC01116 group had inhibited LINC01116 and EZH2 expressions, and increased TPM1 expression in tumor tissues of nude mice." (PMID 33499872, 2021). "The protein expression levels of the indicated seven genes were compared, and it was found that TPM1 was statistically different between the tumor and normal groups; subsequently, we explored the relationship between TPM1 and immune function." (PMID 34180352, 2021). "This suggests that TPM1, a tumor-suppressor gene related to cancer migration and invasion, is a potential target of miR-21 in ESCC." (PMID 33193757, 2020). "MiRNA-21 is another BC-related miRNA that promotes in-vitro and in-vivo tumour growth by targeting PTEN and TPM1 tumour-suppressor genes, whereas it affects metastasis by directly targeting TIMP3, SERPIN5B, PDCD4 and BCL28,9." (PMID 31811234, 2019). "The expression of tropomyosin can be regulated by other factors; for example, miR-21 can down-regulate TPM1 to inhibit tumor growth, and thus miR-21 functions as an oncogene." (PMID 30314482, 2018). "It was proposed that TPM1 is a crucial tumor-suppressing gene, which exhibited a low expression level in many solid tumors." (PMID 28182650, 2017). "In summary, it was demonstrated in this study that TPM1 acted as a tumor-suppressing gene in OSCC, and the TPM1 expression level was related to OSCC prognosis." (PMID 28182650, 2017). "In our opinion, TPM1 is a tumor-suppressing gene, and enhanced TPM1 expression in tumor cell lines is needed." (PMID 28182650, 2017). "It is consistently dysregulated in many types of cancer and is a key factor in tumorigenesis and tumor suppression because it targets tumor suppressor genes such as tropomyosin 1, programmed cell death 4, and phosphatase and tensin homolog." (PMID 25706383, 2015).
tumor (continued). "For example, miR-21 has a role not only in tumor growth, but also in invasion and tumor metastasis by targeting multiple tumor/metastasis suppressor genes such as TPM1, PDCD4 and Maspin in metastatic breast cancer." (PMID 26694467, 2015). "miR-21 also targets the tumor suppressor genes tropomyosin 1 (TPM1), programmed cell death 4 (PDCD4), and Maspin; the latter two have been implicated in the suppression of tumor invasion and metastasis." (PMID 24490161, 2013). "This miRNA appears over expressed in different tumor samples and targets PTEN, PDCD4, TPM1, and Maspin human genes, promoting growth, migration, and invasion in different tumor types." (PMID 23251139, 2012). "Our results confirmed that the mutually exclusive exon pair 7A/7B of TPM1 is differentially spliced in NSCLC such that there is a switch from exon 7B to exon 7A in tumour." (PMID 21118496, 2010). "TPM1 is a tumour suppressor that is involved in cytoskeleton remodelling and that has pro-apoptotic properties." (PMID 21118496, 2010). "Despite the obvious importance of TPM1 in tumour development, data on TPM1 gene expression in clinical samples of CRC samples in comparison to corresponding normal tissue do not exist." (PMID 19678923, 2009). "Several recent studies report that miR-21 downregulates four individual tumor suppressors: phosphatase and tensin homolog; tropomyosin 1; programmed cell death 4; and maspin." (PMID 19267923, 2009). "Our data obtained by real-time PCR show 1.6 times lower expression of TPM1 in CRCs, which supports the current view of TPM1 as a tumour suppressor." (PMID 19678923, 2009). "miR-21 is one of the most highly expressed miRNAs in PDAC and acts as an oncomiR by repressing genes with tumor suppressor functions such as PTEN, PDCD4, and TPM1, thus enhancing tumor growth and gemcitabine resistance, and, therefore, is a potential diagnostic and therapeutic target." (PMID 40699746, 2025). "The tumor suppressor TPM1 is suppressed by miR-21, promoting cancer cell growth." (PMID 38726321, 2024). "Increased expression of ACTA2, FLNA, TAGLN, and TPM1 may promote the transformation of macrophages into M2 in the tumor microenvironment." (PMID 37274283, 2023). "MYC-driven up-regulation of lncRNA ELFN1-AS1 could silence TPM1 through epigenetic, and further promote tumor growth of CRC." (PMID 37161577, 2023). "This is another manifestation of TPM1 as a tumor-suppressive factor." (PMID 37686101, 2023). "In addition, it has been shown that miR-21-5p exerts its oncogenic role by targeting multiple tumor suppressor genes, such as Bcl-2, TPM1, PDCD4, and PTEN." (PMID 37444533, 2023). "Our data suggested the two hub genes, SPARC and TPM1 may have key roles in the PDCA tumor microenvironment by regulating tumor-infiltrating immune cells." (PMID 35477379, 2022). "TPM1 belongs to the tropomyosin family and plays a vital role in cytoskeletal functions, such as cell proliferation, migration, and apoptosis, thereby playing a key role in tumor growth and metastasis." (PMID 35909899, 2022). "Taken together, the data suggested that knockdown of TPM1 could abandon LINC01116 silencing induced tumor inhibition." (PMID 33499872, 2021). "TPM1 inhibits tumor malignant progression by regulating immune cell proliferation and development." (PMID 34180352, 2021). "The expression of miR-183 and TPM1 in tumor tissues of nude mice was examined by RT-qPCR assay." (PMID 33653339, 2021). "Emerging research has revealed that TPM1 may function as a tumor suppressor, highlighting its potential role in tumorigenesis as well as the development of a wide variety of malignancies." (PMID 33653339, 2021).
tumor (continued). "Considering that TPM1 is known as a potent inhibitor of tumor migration and invasion, we determined whether posttranslation silencing of TPM1 is required for miR-21 to promote ESCC migration and invasion." (PMID 33193757, 2020). "Furthermore, miR-21 can downregulate several tumor suppressor genes e.g., PDCD4, MARCKS, and RECK metalloproteinase inhibitor, TPM1 and hence stimulating tumor initiation, invasion, and intravasation." (PMID 32308936, 2020). "In this study, it was revealed initially that TPM1 acted as a tumor suppressing gene in OSCC." (PMID 28182650, 2017). "The tumor progression reduced by hsa-miR-21 down-regulation is mediated by the hsa-miR-21 target genes; the target genes are metastasis-related tumor suppressor genes such as TPM1, Programmed Cell Death 4 (PDCD4) and SERPINB5." (PMID 28793339, 2017). "Tropomyosin-1 (TPM1), which is expressed at a low level, has been considered a prominent tumor-suppressing gene in a variety of solid tumors, although the precise mechanism of the TPM1 gene in OSCC progression remains unknown." (PMID 28182650, 2017). "The aim of this study was to determine whether TPM1 expression is associated with OSCC and prognosis, and if so, what role TPM1 plays in which aspect of tumor biology." (PMID 28182650, 2017). "In addition, there is evidence that the 3'UTR of TPM1 transcripts can activate the tumour-suppressing RNA-dependent protein kinase R and mediate the effects of the potent tumour promoting microRNA, mir21." (PMID 27649540, 2016). "TPM1 and TPM4 genes encode proteins associated with cardiovascular and neoplastic disease." (PMID 27649540, 2016). "TPM1 (tropomyosin alpha-1 chain) is an actin filament-binding protein with diverse biological actions including malignant transformation, and it is considered as a tumor suppressor gene." (PMID 23213280, 2012). "Moreover, it has been demonstrated that tropomysin 1 (TPM1) has tumour suppressor properties and it can revert transformed phenotype." (PMID 19678923, 2009). "So far, SLC26A3, DCN and TPM1 genes have been suggested to have tumour suppressor properties." (PMID 19678923, 2009). "Downregulation of tropomyosin 1 in breast cancer by miR-21 might explain why suppression of miR-21 could inhibit tumor growth, further supporting the notion that miR-21 functions as an oncogene." (PMID 17894887, 2007). "However, SPARC and TPM1 roles in tumor-infiltrating require further investigation." (PMID 35477379, 2022). "MiR-21 has also been linked to human tumor invasion and metastasis by negatively regulating targets that are adversely associated with metastatic capacity, such as PTEN, PDCD4, von Hippel-Lindau (VHL), TIMP3, Tropomyosin 1 (TPM1), and Serpin Family B Member 1 (SEPINB1)." (PMID 34066762, 2021). "This could indicate the association of TPM1, CRYAB, and CASQ2 with tumor progression." (PMID 31991631, 2020). "Our study demonstrated that TPM1 could act as a tumor-suppressing gene in OSCC." (PMID 28182650, 2017). "For instance, miR-21, which is upregulated in breast, lung, gastric, and brain cancers, inhibits tumor suppressors like PTEN, PDCD4, and TPM1, thereby enhancing tumor growth, metastasis, and chemoresistance." (PMID 40259326, 2025). "MiR-21 exerts its oncogenic functions by targeting genes like TPM1, PDCD4, PTEN, and Smad7, enhancing tumor cell growth and inhibiting apoptosis." (PMID 38726321, 2024). "Further studies have shown that overexpression of TPM1 in RCC inhibits tumor cell proliferation and promotes tumor cell apoptosis." (PMID 37686101, 2023). "TPM1, a member of the tropomyosin (TPM) family, has been reported as a tumor suppressor gene in numerous kinds of cancers." (PMID 37854295, 2023). "Collectively, these results imply that AZGP1P2 mediates the stemness and apoptosis of PCSCs and promotes docetaxel therapeutic effect by suppressing tumor growth and metastasis via UBA1/RBM15-mediated TPM1 mRNA decay in CRPC." (PMID 37854295, 2023).